FGF23 (fibroblast growth factor 23)
Diseases named in the same sentence as FGF23 in open-access papers (continued):
Sharing a sentence is not in itself a finding about the gene and the disease.
secondary hyperparathyroidism (continued). "Indeed, FGF-23 has been proposed to be the initial adaptive response to reduced kidney function leading to low 1,25D and secondary hyperparathyroidism in CKD and to be a key initiating factor in CKD-mineral and bone disorder." (PMID 25208316, 2014). "In the studies conducted with hemodialysis studies, FGF-23 levels >7500 ng/L have been found to be important in prediction of refractory secondary hyperparathyroidism; however, effects of the secondary hyperparathyroidism treatment on FGF-23 levels is yet to be cleared." (PMID 25295189, 2014). "With a better understanding of the FGF23-Klotho axis, we believe that new approaches might be developed in the treatment of refractory secondary hyperparathyroidism." (PMID 25295189, 2014). "Today, explanation of the FGF23-Klotho axis is becoming increasingly important in order to reveal unknown aspect of the treatment of refractory secondary hyperparathyroidism." (PMID 25295189, 2014). "There were some studies indicating that serum FGF-23 levels increased following administration of regular active vitamin D and phosphorus binding treatment compared to pretreatment in hemodialysis patients with severe secondary hyperparathyroidism." (PMID 25295189, 2014). "Increased Fgf23 production may have contributed to the development of secondary hyperparathyroidism." (PMID 22629419, 2012). "Moreover, this regimen is associated with well-recognized risks—including secondary hyperparathyroidism, nephrocalcinosis, and gastrointestinal intolerance—and does not address the underlying FGF23-mediated disease mechanism." (PMID 41226894, 2025). "Common complications in CKD include secondary hyperparathyroidism, characterized by high-turnover renal osteodystrophy, with increased bone turnover leading to bone fragility and an increased risk of fractures, involving disturbances in calcium, phosphorus, PTH, vitamin D, and FGF23 levels." (PMID 40447997, 2025). "Some researchers have accordingly hypothesized that inhibition of the activity of the parathyroid FGF23/αKlotho axis by judicious selection and overexpression of specific microRNAs may be an effective strategy for the treatment of secondary hyperparathyroidism." (PMID 40394480, 2025). "In the late stages, this compensatory mechanism may become maladaptive from the loss of renal functions, resulting in a progressive increased FGF23 level, decreased calcitriol levels, hypocalcemia, and associated consequences such as CKD-MBD from a secondary hyperparathyroidism." (PMID 35269640, 2022). "In addition, increased FGF23 production in CKD (due to the impact of secondary hyperparathyroidism, treatment with active vitamin D metabolites, etc.)may contribute to the increased FGF23 plasma levels." (PMID 34065339, 2021). "Thus, reduced FGF23 signalling may explain the resistance to the putative inhibitory effects of FGF23 on the parathyroid glands, but cannot disprove the involvement of FGF23 in the pathogenesis of secondary hyperparathyroidism." (PMID 28094278, 2017). "However, excess FGF23 induces suppression of renal 1,25(OH)2D synthesis and reduction in circulating 1,25(OH)2D, actions thought to be critical to the development of secondary hyperparathyroidism." (PMID 26588476, 2015). "According to this opinion, this might be caused by insufficient suppression of parathyroid secretion by the parathyroid gland that remains unresponsive to the calcitriol therapy as well as elevated FGF-23 levels that remain unresponsive in refractory secondary hyperparathyroidism." (PMID 25295189, 2014). "Since enterocytes rely heavily on 1,25D to facilitate dietary calcium absorption, FGF23-mediated reductions in 1,25D levels, which begin early in the course of CKD, contribute to development of secondary hyperparathyroidism." (PMID 39688907, 2024).
secondary hyperparathyroidism (continued). "Although the progressive rise in FGF-23 helps maintain normophosphataemia until the later stages of CKD, it leads to the suppression of calcitriol production, promoting secondary hyperparathyroidism." (PMID 39684548, 2024). "Despite extensive research interest in FGF-23, debate remains over whether the observed relationship with MACE is likely to be causal or a result of unmeasured confounding factors, possibly reflecting differences in kidney function, secondary hyperparathyroidism, or treatment for renal bone disease." (PMID 38162538, 2024). "The levels of FGF23 and PTH increase progressively and subsequently drive secondary hyperparathyroidism and CKD-MBD." (PMID 35622784, 2022). "The mechanisms leading to secondary hyperparathyroidism in CKD include not only the reduction in functional kidney mass and FGF23-induced suppression of vitamin D hormone synthesis, but also skeletal resistance to PTH." (PMID 34290280, 2021). "The rise in FGF-23 levels in CKD, suppresses vitamin D activation by the kidneys, leading to secondary hyperparathyroidism." (PMID 30356327, 2018). "These higher than normal levels of PTH in cKO mice suggest the involvement of multiple factors, other than FGF23/αKlotho/FGFR signalling, in the pathogenesis of secondary hyperparathyroidism." (PMID 28094278, 2017). "Therapy with doxercalciferol increases expression of full-length FGF23 as well as total DMP1 and decreases the presence of the 57 kDa DMP1 fragment in the bone of pediatric dialysis patients with secondary hyperparathyroidism." (PMID 25774916, 2015). "In advanced CKD, FGF23 no longer maintains phosphate homeostasis and the suppression of 1,25(OH)2D production exerted by FGF23 induces PTH elevation, resulting in secondary hyperparathyroidism (SHPT)." (PMID 23705925, 2013). "Since burosumab inhibits the inhibitory effect of FGF23 on PTH, burosumab may result in increased PTH secretion and the development of secondary hyperparathyroidism." (PMID 40922882, 2025). "Osteopenia and osteoporosis are also highly prevalent in HD patients due to abnormal CKD-related homeostasis, elevated phosphate and fibroblast growth factor-23 (FGF-23), and reduced vitamin D and calcium levels, leading to secondary hyperparathyroidism and impaired bone remodeling." (PMID 41302091, 2025). "This syndrome comprises vitamin D deficiency, vascular calcification, abnormalities in bone turnover, altered metabolism of calcium and phosphate, and increased levels of fibroblast growth factor-23 (FGF-23) and parathyroid hormone (PTH), known as secondary hyperparathyroidism (SHPT)." (PMID 40525801, 2025). "Furthermore, ferric citrate reduced FGF23 levels and lowered the PTH level, thereby exerting effect on secondary hyperparathyroidism." (PMID 40362897, 2025). "While additional investigation is needed to understand the mechanism of FGF23 reduction in VillinCreERT2Cyp24fl/fl mice with kidney damage, these results support inhibition of intestinal CYP24A1 as an approach to mitigate secondary hyperparathyroidism and FGF23 excess in patients with CKD." (PMID 39688907, 2024). "Consequently, the auto-/paracrine effects of FGF23 on bone cells, mediated by high levels of circulating FGF23, is another possible pathogenesis of CKD-MBD, in addition to secondary hyperparathyroidism." (PMID 35269640, 2022). "In addition, ferric citrate reduced FGF23 levels by more than half and also lowered the intact PTH (iPTH) level, thereby exerting effect on secondary hyperparathyroidism." (PMID 34069053, 2021). "Vitamin D can regulate secretion of some hormones, including parathyroid hormone (PTH), insulin, and fibroblast growth factor 23 (FGF23), and the effects on PTH secretion are facilitated by using vitamin D analogues in the clinical treatment of secondary hyperparathyroidism." (PMID 32316584, 2020). "In Fgf23/VDR compound mice lacking Fgf23, 5/6-Nx induced secondary hyperparathyroidism and bone loss." (PMID 29942284, 2018).
secondary hyperparathyroidism (continued). "Recent studies have shown that coreceptors Klotho and FGFR1c, which activate FGF-23, decreased in uremic parathyroid hyperplasia, and high serum FGF-23 levels could be explained by Klotho-FGFR1c complexes of secondary hyperparathyroidism." (PMID 25295189, 2014). "Therefore, a correlation has been considered between refractory secondary hyperparathyroidism and FGF-23 levels and importance of FGF-23 in the treatment was begun to be emphasized." (PMID 25295189, 2014). "Accordingly, both FGF-23 and PTH are involved in the adaptive response to ensuing secondary hyperparathyroidism, with the difference that PTH accentuates the calcitriol deficiency but FGF-23 does not." (PMID 21234310, 2010). "In addition, the attenuation of secondary hyperparathyroidism was significantly higher in the groups receiving phosphate binders compared with the placebo group, but phosphate binders did not affect the FGF23 level." (PMID 34069053, 2021). "As the rise in FGF-23 precedes the rise in parathyroid hormone and serum phosphate, the question may be raised whether the rise in FGF-23 is not the primary pathophysiologic event in the development of secondary hyperparathyroidism." (PMID 29316724, 2018). "Although the doses and duration of the therapies were similar in all of the patients in our study, high serum levels in the patients with elevated serum PTH and FGF-23 levels could be insufficient in suppression of PTH secretion and resulted in the development of secondary hyperparathyroidism." (PMID 25295189, 2014). "One possible explanation for the lack of an FGF23 response is that the suppression of FGF23 may function as a compensatory mechanism to prevent further reductions in serum calcium levels in the setting of secondary hyperparathyroidism and increased skeletal demand in Graves’ disease." (PMID 41190261, 2025).
Hypertension (120 papers, 2012 to 2026). The presence of chronic increased pressure in the systemic arterial system. "In a cohort study, higher levels of FGF23 were shown to be associated with increased systolic and diastolic blood pressure during a 10-year follow-up, with 35.2% of participants developing hypertension." (PMID 41426862, 2025). "In Model 4, which additionally included eGFR and urinary ACR, knee extension strength, eGFR, and the presence of hypertension remained significantly associated with circulating FGF23 levels." (PMID 41038963, 2025). "Klotho deficiency is mechanistically linked to the development of hypertension through several interconnected pathways involving FGF23, the renin–angiotensin–aldosterone system (RAAS) and sympathetic nervous activity." (PMID 41303567, 2025). "Hyperparathyroidism, raised FGF-23, vitamin D deficiency can be the results of excessive inorganic phosphate intake, which were closely associated with increased risk of hypertension." (PMID 36364791, 2022). "Elevated FGF23 levels have also been associated with several forms of adverse cardiovascular outcomes, including subclinical atherosclerotic disease, hypertension, left ventricular hypertrophy, and other cardiovascular events." (PMID 35629299, 2022). "When using the lowest sex-specific tertile of FGF23 as the reference group, we observed that the highest sex-specific tertile of FGF23 was associated with a higher risk for incident hypertension (HR 1.27 (95% CI 1.07–1.51), p = 0.02)." (PMID 34960084, 2021). "In CKD, several studies showed that increased FGF23 or serum phosphate was closely associated with hypertension." (PMID 34861810, 2021). "Observational studies have shown that increased levels of FGF23 are associated with incident hypertension in the general population." (PMID 34960084, 2021). "Lastly, this study evaluated the potential mediation effect of FGF23 for the association between urinary potassium excretion and incident hypertension." (PMID 34960084, 2021). "In this subset from the PREVEND cohort without hypertension at baseline, it was found that both low potassium excretion and high FGF23 were associated with incident hypertension, in line with previously published studies." (PMID 34960084, 2021). "The lowest sex-specific urinary potassium excretion tertile (HR 1.18 (95% CI 1.01–1.37)), and the highest sex-specific tertile of FGF23 (HR 1.17 (95% CI 1.01–1.37)) were each associated with incident hypertension, compared with the reference tertile." (PMID 34960084, 2021). "Remarkably, FGF23 serum levels are also linked to incident hypertension in the general population independently of kidney function suggesting that other factors drive its overproduction in modern society." (PMID 34050126, 2021). "MPR and E/e* remained significantly associated with FGF-23 when the model was adjusted for age, sex, eGFR and known hypertension (P < 0.01 for both), whereas UACR lost its significance after adjustment." (PMID 32998751, 2020). "In a linear model adjusted for age, sex, eGFR and hypertension, increasing FGF-23 was associated with decreased MPR (P < 0.01, R2 = 0.11) and increased E/e* (P < 0.01, R2 = 0.07)." (PMID 32998751, 2020). "In the CARDIA (Coronary Artery Risk Development in Young Adults) study, the association of C-terminal FGF23 (cFGF) levels with hypertension was analyzed in a younger (18–30 years), more multiethnic population." (PMID 31698866, 2019). "This shows the importance of controlled dietary phosphate intake and underlines that FGF23 and phosphate represent promising therapeutic targets in treating hypertension in CKD patients." (PMID 31698866, 2019). "To date, there is evidence supporting a disordered renin–angiotensin aldosterone system, altered calcium and phosphate metabolism (causing high levels of fibroblast growth factor 23 and parathyroid hormone) and hypertension." (PMID 29024966, 2018).
Hypertension (continued). "Furthermore, given the potential role of hypertension, serum magnesium, FGF-23, and ALP in increasing disease risk, future research should prioritize these factors in subsequent analyses to further validate and substantiate existing findings." (PMID 40314886, 2025). "The observed alterations in FGF-2, FGF-19, FGF-22, and FGF-23 concentrations—particularly their associations with hypertension, obesity, nephropathy, and joint degeneration—support their role not only in the pathogenesis but also in the clinical stratification of diabetic complications." (PMID 40943671, 2025). "Moreover, higher FGF-23 levels independently correlate with an increased risk of incident hypertension and all-cause mortality over time." (PMID 39989455, 2025). "Hyp mice are characterized by chronic elevation of FGF23 and may, therefore, serve as a model to investigate the pathophysiology of hypertension in diseases associated with excessive FGF23 secretion." (PMID 35884995, 2022). "Second, since the FGF23/Klotho axis is associated with hypertension and CVD, we were unable to determine whether the clinical impact of Klotho on mortality was reliant on or independent of FGF23." (PMID 36457804, 2022). "Based on the sodium-conserving function of FGF23, elevated circulating FGF23 may predispose subjects to the development of hypertension through volume expansion." (PMID 35884995, 2022). "Increasing potassium intake, and reducing plasma FGF23 could be independent targets to reduce the risk of hypertension in the general population." (PMID 34960084, 2021). "Furthermore, low urinary potassium excretion and high FGF23 are independently associated with incident hypertension, but FGF23 was not a mediating factor between urinary potassium excretion and incident hypertension." (PMID 34960084, 2021). "Although experimental data suggests that FGF23 may cause hypertension, a direct relationship between cognition and altered mineral metabolism is controversially discussed." (PMID 34536161, 2021). "This study addressed whether FGF23 is a mediator of the association between urinary potassium excretion and incident hypertension." (PMID 34960084, 2021). "Furthermore, low urinary potassium excretion, and high FGF23 levels were each associated with a higher risk of incident hypertension." (PMID 34960084, 2021). "Clinical studies regarding the association of high FGF23 and hypertension are controversial." (PMID 35118076, 2021). "The underlying cause might be differences in the mineral metabolism and FGF23 concentrations, together with systemic alterations such as hypertension and inflammation." (PMID 31698866, 2019). "These clinical studies provide evidence that FGF23 might be a causal factor in the development of hypertension in CKD patients." (PMID 31698866, 2019). "FGF23 has been found to directly cause phosphate-induced vascular calcification, whereas another hypothesis suggests that elevated FGF23 levels could be associated with atherosclerosis through hypertension." (PMID 35629299, 2022). "However, it has not yet been assessed whether urinary potassium excretion, as proxy for dietary potassium intake, is inversely associated with FGF23, and whether FGF23 mediates the association between urinary potassium excretion and incident hypertension." (PMID 34960084, 2021). "The aim of the current study was to address whether 24-h urinary potassium excretion, reflecting dietary potassium intake, is associated with FGF23, and whether FGF23 mediates the association between urinary potassium excretion and incident hypertension in the general population." (PMID 34960084, 2021). "Experimental data suggest that FGF23 increases sodium reabsorption via upregulation of the amiloride-sensitive epithelial sodium channel (ENaC) in the renal collecting tubule and may thereby cause hypertension." (PMID 34536161, 2021).